SIRT6 (sirtuin 6)
Diseases named in the same sentence as SIRT6 in open-access papers (continued):
Sharing a sentence is not in itself a finding about the gene and the disease.
renal fibrosis (13 papers, 2017 to 2025). A final common manifestation of a wide variety of chronic kidney diseases characterized by glomerulosclerosis and tubulointerstitial fibrosis. "For example, older Sirt6 knockout mice showed improved renal fibrosis, and Sirt6 deficiency in kidneys exacerbated podocyte injury and proteinuria in DN." (PMID 34122724, 2021). "Our results suggest that the loss of Sirt6 in proximal tubules aggravates UUO-induced renal fibrosis and that Sirt6 activator MDL-800 mitigates UUO-induced renal tubulointerstitial inflammation and fibrosis by regulating Sirt6-dependent β-catenin acetylation and ECM protein transcription." (PMID 35563783, 2022). "Sirtuin 6 (SIRT6) can reduce cellular oxidative stress, inflammatory responses and renal fibrosis, thereby maintaining cellular homeostasis and delaying the progression of kidney diseases." (PMID 41463452, 2025). "This expanding understanding of the roles of Sirt1, Sirt3, and Sirt6 in renal fibrosis provides potential avenues for targeted therapeutic interventions in kidney diseases." (PMID 38929505, 2024). "Recent studies have shown that Sirt6 knockdown exacerbates renal fibrosis after UUO and that the protective mechanism of Sirt6 is the inhibition of β-catenin expression." (PMID 38929505, 2024). "Taken together, our findings suggest that SIRT6/HIPK2 axis is a potential target to intervene renal fibrosis and delay CKD progression." (PMID 36172184, 2022). "In a caloric restriction (CR) mouse model, SIRT6 slows the development of renal fibrosis by inhibiting NF-κB signaling, which in turn slows the proliferation and senescence of WI38 fibroblasts." (PMID 36148005, 2022). "In the kidney, SIRT6 plays an important role in podocyte injury and renal fibrosis in podocytes and proximal epithelial tubular cells." (PMID 32932720, 2020). "Mdl-800 (Sirt6 agonist) attenuates renal fibrosis and inflammation in UUO." (PMID 38929505, 2024). "SIRT6 deficiency significantly activates TGF-β signaling and organ fibrosis and the knockdown of SIRT6 aggravates unilateral ureteral obstruction (UUO)-induced renal fibrosis." (PMID 36831402, 2023). "Since improvement in renal fibrosis can also be seen through further SIRT6 overexpression, we thought it might be a compensatory mechanism." (PMID 36172184, 2022). "Meanwhile, knockdown of SIRT6 aggravates unilateral ureteral obstruction-induced renal fibrosis." (PMID 36172184, 2022). "However, understanding the role of proximal tubule-specific Sirt6 in renal fibrosis remains elusive." (PMID 35563783, 2022). "In a recent study, selective deletion of Nampt in proximal tubule cells of STZ-induced diabetic mice led to downregulation of SIRT6, which was accompanied by thickening of the tubular basement membrane, type IV collagen deposition, enhanced renal fibrosis, and albuminuria." (PMID 32932720, 2020). "However, the role of proximal tubule-specific Sirt6 in renal fibrosis remains elusive." (PMID 35563783, 2022). "In renal tubular epithelial cells, SIRT6 binds to β-catenin and mediates histone deacetylation near the promoters of fibronectin, MMP7, and snail, exerting a protective effect against renal fibrosis by inhibiting their transcription." (PMID 36148005, 2022). "To further investigate the inhibition of renal fibrosis and aortic calcification by exosomes, we assessed the characteristics of HMGB1 and SIRT6 in the mouse model of CKD." (PMID 33849640, 2021). "Considering the role of Sirt6 in EMT and renal fibrosis in DN, we hypothesized that it might ameliorate renal fibrosis by inhibiting EMT and tubular injury." (PMID 34122724, 2021).
acute myeloid leukemia (12 papers, 2018 to 2025). Acute myeloid leukemia (AML) is a group of neoplasms arising from precursor cells committed to the myeloid cell-line differentiation. "SIRT6 is overexpressed in CD34+ hematopoietic progenitors and multiple myeloma in patients with acute myeloid leukemia, and high SIRT6 levels are associated with poor prognosis." (PMID 35463332, 2022). "Numerous previous studies have confirmed that SIRT6 can function as an oncogene in skin squamous cell carcinoma, multiple myeloma and acute myeloid leukaemia." (PMID 33037850, 2020). "Due to our previous results, the expression level of SIRT6 enzyme negatively correlates with the level of the tumor suppressor miR-124 in acute myeloid leukemia (AML)." (PMID 32117717, 2020). "In acute myeloid leukemia cells, inhibition of SIRT6 disrupts DNA damage repair mechanisms and increases sensitivity to daunorubicin and Ara-C." (PMID 30524965, 2018). "However, several recent studies have reported that SIRT6 functions as a tumor promoter in other human cancers, such as skin squamous cell carcinoma, papillary thyroid cancer and acute myeloid leukemia (AML)." (PMID 31817470, 2019). "The biological relevance of SIRT6 in acute myeloid leukemia (AML) includes frequent up-regulation in tumor cells compared with normal CD34+hematopoietic progenitors." (PMID 29966233, 2018). "ChIP-Seq analysis of bone marrow cells derived from six acute myeloid leukemia (AML) patients and treated with the nucleoside analog DAC induced genome-wide acetylation changes in H3K9, the physiological substrate for SIRT6." (PMID 32587297, 2020). "Moreover, FDA-approved DNA hypomethylating agents (DHAs) such as decitabine (DAC) and 5-azacytidine (5AC), widely used in acute myeloid leukemia (AML), have been shown to selectively activate SIRT6 enzymatic activity without significantly affecting other sirtuin isoforms." (PMID 41463311, 2025).
Cerebral ischemia (12 papers, 2016 to 2025). Restriction of arterial blood supply to the brain associated with insufficient oxygenation to support the metabolic requirements of the tissue. "Similarly, decreased expression of SIRT6 was associated with the release of HGMB1 after adult cerebral ischemia." (PMID 34867200, 2021). "Role of Baicalein in Neuroprotection: The research shows that baicalein alleviates cerebral ischemia-reperfusion injury by upregulating SIRT6 expression, promoting FOXA2 deacetylation, and ultimately inhibiting ferroptosis." (PMID 39299807, 2024). "The inhibition of Cezanne increased SIRT6 levels and conferred neuroprotection after cerebral ischemia injury in rats and in cultured neurons after OGD insult." (PMID 38474013, 2024). "As a key histone deacetylase, SIRT6 decreased significantly during cerebral ischemia, promoting the release of HMGB1." (PMID 37627275, 2023). "In the context of cerebral ischemia, energy restriction-induced SIRT6 has been found to inhibit TXNIP transcription and promote angiogenesis, which is critical for tissue repair and recovery after cerebral ischemia." (PMID 37627275, 2023). "Our study demonstrated that ER-mediated upregulation of SIRT6 inhibited microglia activation and potentiated angiogenesis in cerebral ischemia via suppressing TXNIP." (PMID 35562171, 2022). "ER mimetics or SIRT6 overexpression alleviated cerebral ischemia and reperfusion (I/R)-induced injury in vitro." (PMID 35562171, 2022). "In conclusion, we have demonstrated that ER-mediated upregulation of SIRT6 inhibited microglia activation and potentiated angiogenesis in cerebral ischemia via suppressing TXNIP in vitro." (PMID 35562171, 2022). "SIRT6 protected the brain from cerebral I/R injury and contributed to neurogenesis after cerebral ischemia." (PMID 30791908, 2019). "Moreover, recent studies showed that Sirt6 overexpression inhibited the inflammatory response and thus ameliorate neurological deficits in intracerebral hemorrhage rats and cerebral ischemia and reperfusion rats." (PMID 36978961, 2023). "SIRT6 has also been shown to protect the adult brain from cerebral ischemia/reperfusion injury." (PMID 34867200, 2021). "The effect of SIRT6 in cerebral ischemia and oxygen/glucose deprivation (OGD) has been reported, however the role of SIRT6 in oxidative stress damage remains unclear." (PMID 26983852, 2016). "TXNIP might be an important downstream molecule of SIRT6 during cerebral ischemia." (PMID 35562171, 2022). "Ultimately, SIRT6 could have a neuroprotective role in the setting of acute brain ischemia." (PMID 36443316, 2022). "Another study showed that the overexpression of SIRT6 increased nuclear NRF2 expression and reduced oxidative stress in the cerebral ischemia/reperfusion (I/R) model." (PMID 35517808, 2022). "SIRT6 and TXNIP might be involved in the regulation of cerebral ischemia-induced microglial activation and angiogenesis." (PMID 35562171, 2022). "In addition, energy restriction-induced upregulation of Sirt6 could inhibit microglial activation and enhance angiogenesis by suppressing TXNIP in cerebral ischemia." (PMID 36978961, 2023). "In this study, we found that IF or ER mimetics protected against cerebral ischemia-induced impairment and microglial activation and potentiated middle cerebral artery occlusion (MCAO)-induced angiogenesis, and accompanied by changes in expression of SIRT6, TXNIP, and NLRP3 inflammasome." (PMID 35562171, 2022).
osteoporosis (12 papers, 2016 to 2025). A condition of reduced bone mass, with decreased cortical thickness and a decrease in the number and size of the trabeculae of cancellous bone (but normal chemical composition), resulting in increased fracture incidence. "Sirt6 deficiency may cause senile osteoporosis through the promotion of osteoclastogenesis and inhibition of osteoblastogenesis in mice via activation of NF-κB/CatK signaling pathway." (PMID 31715585, 2019). "This article reviews the impact of various aspects of mitochondrial quality control on osteoporosis, focusing on how SIRT1, SIRT3, and SIRT6 can improve osteoporosis by regulating mitochondrial protein homeostasis, biogenesis, and mitophagy." (PMID 38264287, 2023). "Among these investigations, there is a predominant emphasis on SIRT1 and its association with osteoporosis, followed by attention toward SIRT3 and SIRT6." (PMID 38264287, 2023). "In brief, SIRT1 and SIRT6 can inhibit the development and progression of osteoporosis by resisting oxidative stress, aging and regulating bone metabolism." (PMID 36581622, 2022). "miR-128 inhibits osteoblast differentiation in osteoporosis by downregulating SIRT6 expression, thus accelerating the development of osteoporosis." (PMID 35008515, 2021). "Additionally, oxidative stress may induce downregulation of the nuclear regulatory enzyme, sirtuin 6 (Sirt6), which is associated with the development of senile osteoporosis through the induction of osteoclastogenesis via the regulation of the NF-κB/CatK signaling pathway." (PMID 31715585, 2019). "To further confirm that SIRT6 is a potential target for osteoporosis treatment, we next examined the expression level of SIRT6 in the primary MSCs from the bone marrow of both sham and OVX mice." (PMID 28860594, 2017). "Osteoporosis is yet another age-related disorder in mammals, and recent studies have found that Sirt6 prevents osteoporosis, but the mechanism remains unclear." (PMID 33442387, 2020). "However, further observation on the effects of FLL on Sirt6 expression in response to chronic injection of TMAO is still needed, which will provide strong evidence on underlying mechanisms of this herb on senile osteoporosis." (PMID 31715585, 2019). "To verify whether SIRT6 was involved in osteoporosis, we next established OVX mice model." (PMID 28860594, 2017). "For instance, in the case of osteoporosis, SIRT6-mediated deacetylation and downregulation of HDAC2 were both proved to be helpful to mitigate osteoporosis, while the former led to increased ERα level and the latter led to promoted acetylation of histone H3." (PMID 34326880, 2021). "Consequently, this article undertakes a comprehensive examination of the impacts of diverse facets of mitochondrial quality control on osteoporosis, as well as the influence of SIRT1, SIRT3, and SIRT6 on osteoporosis through the regulation of mitochondrial quality control." (PMID 38264287, 2023). "Nonetheless, the present study provides the first evidence that FLL may protect against senile osteoporosis through regulation of gut microbiota diversity and the levels of TMAO and Sirt6, and therefore could be a new source for screening anti-aging drug candidates." (PMID 31715585, 2019).
papillary thyroid cancer (12 papers, 2018 to 2025). "In thyroid papillary carcinomas, higher expression of SIRT6 was associated with increased risk of lymph node metastasis." (PMID 30524965, 2018). "SIRT6 was previously reported to promote ROS‐induced ERS through high activation of PERK/eIF2α signalling in SIRT6‐overexpression papillary thyroid cancer cells." (PMID 37598403, 2023). "Sirt6/Hif-1α axis promotes papillary thyroid cancer progression by inducing epithelial-mesenchymal transition (EMT)." (PMID 32711549, 2020). "In papillary thyroid cancer, SIRT6 promotes tumorigenesis by enhancing HIF-1α stability and prolonging its protein half-life." (PMID 31817470, 2019). "In our previous research, we also found SIRT6 increased ROS in papillary thyroid cancer B-CPAP15." (PMID 33436551, 2021). "Our early work infirmed that SIRT6 promotes papillary thyroid cancer aggression." (PMID 30675128, 2019). "This study examined whether SIRT6 promotes epithelial–mesenchymal transition (EMT) of papillary thyroid cancer through hypoxia inducible factor-1α (HIF-1α)." (PMID 30675128, 2019). "The SIRT6/HIF-1α axis could be a new therapeutic target and diagnostic marker of papillary thyroid cancer." (PMID 30675128, 2019). "Previously, SIRT6 was reported to promote an aggressive phenotype and the EMT in papillary thyroid cancer, which was consistent with our findings." (PMID 35251169, 2022). "Similar result was also acquired in VSMC and papillary thyroid cancer cell lines TPC-1 and B-CPAP26, which indicated a universal promotion of SIRT6 at HIF-1α." (PMID 33436551, 2021). "As shown in our previous study, SIRT6 promotes an aggressive phenotype and the epithelial-mesenchymal transition (EMT) in papillary thyroid cancer (PTC)." (PMID 32983963, 2020). "In papillary thyroid cancer (PTC), SIRT6 increases generation of reactive oxygen species to promote the Warburg effect in PTC cells, and high levels of SIRT6 reduce expression of E-cadherin, thereby promoting the invasion and migration of PTC cells and promoting cancer development." (PMID 35463332, 2022). "In this study, we examined the relationship between SIRT6 and EMT in papillary thyroid cancer." (PMID 30675128, 2019).
steatosis (12 papers, 2011 to 2025). Increased lipid within the cytoplasm of cells. "In mice and patients with simple steatosis that exhibit slightly lower levels of SIRT6, most ACSL5 proteins are deacetylated by cytoplasmic SIRT6." (PMID 36880305, 2023). "Taken together, these data suggest that knocking down SIRT6 is sufficient to aggravate FFA-induced steatosis and to dampen the protection conferred by overexpressing MEG3." (PMID 35256601, 2022). "SIRT6 knockout (KO) in mice attenuated the effect of ATL I on suppressing OA&PA-induced steatosis in the MPHs of SIRT6 KO mice." (PMID 36558977, 2022). "Because a variety of molecules in the liver are supposed to mediate the dysregulation of lipid metabolism under ER stress, we sought to determine which genes or pathways were involved in the attenuation of steatosis by Sirt6." (PMID 31541078, 2019). "The present study was designed to test whether RGZ alters hepatic Sirt1 and whether Sirt1 and/or Sirt6 have a regulatory role in the protective effects of rosiglitazone (RGZ) on hepatocyte steatosis." (PMID 25133775, 2014). "The aim of this study was to address whether rosiglitazone (RGZ) alters hepatic Sirt1 and whether Sirt1 and/or Sirt6 have a regulatory role in the protective effects of RGZ on hepatocyte steatosis." (PMID 25133775, 2014). "Besides, we found that Sirt6-LKO mice manifest features of steatosis in the tumor region, suggesting this alteration could drive the development of carcinomagenesis." (PMID 38332150, 2024). "Another study demonstrated that SIRT6 overexpression in liver reduced steatosis, inflammation, and fibrosis caused by a HFHF diet, indicating the SIRT6 activator may be a promising therapeutic direction for treating NASH by reducing oxidative stress and inflammation." (PMID 37834101, 2023). "Taken together, our results suggest that ATL I acts as a promising compound that activates SIRT6/PPARα signaling and attenuates the NLRP3 inflammasome to ameliorate hepatic inflammation and steatosis." (PMID 36558977, 2022). "The knockdown of Sirt6 aggravated hepatocyte fat accumulation as shown by increased TG levels, and suppressed the favorable effects of RGZ on hepatocyte steatosis." (PMID 21373642, 2011). "In a hepatocyte steatosis model with PA treatment, the regulatory effects of RGZ on Sirt1 were significantly blunted by Sirt6 knockdown, which suggests that up-regulation of Sirt1 by RGZ was partially dependent on Sirt6." (PMID 25133775, 2014). "On the other hand, RGZ’s effects on Sirt6 were not altered by Sirt1 knockdown in a hepatocyte steatosis model." (PMID 25133775, 2014). "Our results demonstrate that Sirt1/6 are involved in the RGZ-mediated effects on hepatocyte steatosis, and the regulatory effects of Sirt1 and Sirt6 are not synergistic but compensatory for improving hepatocyte steatosis." (PMID 25133775, 2014). "We also provided an alternative mechanism by which ATL I binds with SIRT6 to activate PPARα and its target genes and suppresses inflammatory factor release by attenuating NFκB-mediated NLRP3 inflammasome formation, which, together, attenuate hepatic inflammation and steatosis." (PMID 36558977, 2022).